CD4 (CD4 molecule)
Diseases named in the same sentence as CD4 in open-access papers (continued):
Sharing a sentence is not in itself a finding about the gene and the disease.
cancer (continued). "The proportion of peripheral ICOS+CD4+ T cells is associated with irAE incidence in patients with cancer." (PMID 40198121, 2025). "Building on previous findings, we observed strong positive correlations between the risk score and key signatures of the matrisome and cancer-associated fibroblasts (CAFs), whereas an inverse correlation was observed with activated CD4+ T cells." (PMID 40959429, 2025). "EPIC analysis showed a similar trend, with high-IEScore patients enriched in CD4+ T cells, macrophages, cancer-associated fibroblasts and endothelial cells were more abundant in high-IEScore patients." (PMID 40842996, 2025). "GSDMD activation in intratumoral CD4+ T cells is associated with favorable prognosis and improved response to anti–PD-1 immunotherapy in human cancers." (PMID 40759573, 2025). "Immune cell infiltration analysis indicated that elevated RASD1 expression is associated with an increased infiltration of CD4+ T cells and myeloid-derived dendritic cells in cancer." (PMID 40362656, 2025). "The endosomal deubiquitylase, USP8, interacts with CTLA4, and its loss enhances CTLA4 ubiquitylation in cancer cells, mouse CD4+ T cells, and cancer cell–derived exosomes." (PMID 39404738, 2025). "Increased levels of CD68 + and CD4 + FOXP3 + cells (above the 75th percentile) were linked to worse cancer-specific survival (CSS) in patients with ccRCC." (PMID 39751643, 2025). "Memory CD4+ T cells are involved in the immune response and have been associated with better prognosis in various cancers." (PMID 40547309, 2025). "The cell type fractions in the TME were relatively similar between the metastatic sites, except for cancer‐associated fibroblasts (CAFs), B cells, endothelial cells, and CD4+ T cells." (PMID 39739693, 2025). "Previous research demonstrated that both Vif and Vpr expression causes cell cycle arrest and cytotoxicity in CD4 +T cells and as well as many cancer cell lines." (PMID 40080415, 2025). "Our study demonstrates the importance of capturing the dynamic nature of CD4+ T cells in understanding disease risk, and prioritises genes for further investigation in cancer prevention research." (PMID 40321251, 2025). "In the escape phase, cancer cells select immunosuppressive cells, including myeloid-derived suppressor cells (MDSCs), regulatory CD4+FOXP3+ T cells (Treg cells), and cancer-associated macrophages." (PMID 41155765, 2025). "Cytotoxic CD4+ T cells have been identified in cancers and associated with GZMB and Perforin (PRF) expression via the transcription factor EOMES." (PMID 40492347, 2025). "Recent studies have emphasized the crucial roles of CD4+ T cells, MDSCs, neutrophils, and macrophages in cancer immunotherapy, underlining the importance of immune cells in therapeutic responses." (PMID 40191190, 2025). "In human cancers, cDC1 gene signatures associated with CD4+ T cell help were positively correlated with overall survival and response to immunotherapy." (PMID 40878038, 2025). "The CIBERSORT and TIDE algorithms were conducted to predict TME and the significant difference of CD4 + T cells, B cells, neutrophils, and cancer-associated fibroblasts (CAFs) between the high and low MS group (all p < 0.01)." (PMID 40694220, 2025). "The expression of PHF6 positively associated with resting-memory CD4+ T cells, while it was negatively correlated with activated NK cells across many cancer types." (PMID 41515604, 2025). "This is comparable to several studies that have found a low CD4 cell count of less than 200 cells to be associated with a significantly increased cancer risk." (PMID 39869644, 2025). "Among CD4+ T cells implicated in cancer immunology, T helper 1 (Th1) cells and Tregs promote and suppress antitumor immunity in response to cancer immunotherapies, respectively." (PMID 39782693, 2025).
cancer (continued). "Among these IRATs, many studies have highlighted TRTs CXCL13+ T cells (CD4+/CD8+) as targets for cancer immunotherapy due to their association with improved clinical outcomes in many cancers." (PMID 40054456, 2025). "It was inversely linked to the relapse-free survival of the white, and B-cell-enriched cancer patients, while the converse was true for the cancer patients with low mutation burden, decreased B-cells, basophils and CD4+ T cells (p < .05)." (PMID 38241178, 2024). "We recently identified cDC1s with a transcriptomic imprint of CD4+ T-cell help, specifically in T-cell-infiltrated human cancers, and these cells were associated with a good prognosis and response to PD-1-targeting immunotherapy." (PMID 38383773, 2024). "PLEK2 expression was positively associated with the infiltration of cancer-associated fibroblasts (CAFs), CD4 T cells, macrophages, and natural killer (NK) cells, but negatively associated with CD8 T cells and B cells." (PMID 39546161, 2024). "Our analysis showed that AEG-1 was associated with immune cell infiltration in various cancers, from T cell NK to CD4+Th1 and T cell CD4+Th2." (PMID 39483471, 2024). "These patients also exhibit increased immunomodulatory and neurotrophic cancer-associated fibroblasts (CAFs); more CD4+ T cells, monocytes, and mast cells; and reduced immune exhaustion gene expression." (PMID 38798691, 2024). "The premise for the excitement over identifying cancer-specific mutations using DNA sequencing was that it would eliminate the cumbersome step of having to generate cancer-specific CD8+ or CD4+ T cells to get to the neoepitopes." (PMID 38426497, 2024). "Following cell annotation in CellMarker2.0, these 23 cell clusters were merged into 9 cell types, including CD8 T cells, CD4 T cells, plasmocytes, monocytes, M2 macrophages, osteoblast, endothelial, cancer‐associated fibroblasts (CAFs) and cancer cells." (PMID 38774995, 2024). "Here, we elucidated that role of stearoyl-CoA desaturase (SCD) increased by treatment with cancer-associated fibroblast (CAF) supernatant in CD4+ T cells on their subset differentiation and activity of CD8+ T cells." (PMID 39543650, 2024). "In the GTEM-SEMI-CVID Registry, older age, immune dysregulation, previous immunosuppressant therapies, higher IgM levels, and lower CD4 cell counts at diagnosis were independently associated to malignancy in CVID from a multivariable approach." (PMID 39478863, 2024). "Th2 CD4+ polarization has been shown to be a result of cancer-associated fibroblast mediated secretion of thymic stromal lymphopoietin and correlates to reduced survival." (PMID 39044834, 2024). "Upregulated expression of BTLA on CD8+ and CD4+ T cells in the TME was associated with unfavorable prognoses for patients with various types of cancer." (PMID 38835768, 2024). "A previous study has demonstrated that TSPAN11 was downregulated in pan-cancer and positively associated with CD4 + T cells, macrophages, neutrophils, and dendritic cells." (PMID 38167072, 2024). "Elevated NSG2 levels both in cancer and stroma cells were linked to increased CD4+ T, CD8+ T, and Lamp3+ dendritic cells infiltration in stromal regions (P < 0.05)." (PMID 39493764, 2024). "EDNRA was evidently associated with TCGA pan‐cancer, including mast cells, CD4+ T cells, NK cells, macrophages, monocytes, dendritic cells, plasma cells, and CD8+ T cells." (PMID 39601333, 2024). "Results of CIBERSORT suggested that risk score affected the infiltration proportions of M2, T cells CD4 memory activated, and plasma cells, which were strongly linked to the prognosis of patients with malignant tumors." (PMID 38217543, 2024). "Consistent with prior reviews, our investigation shows that high infiltration of CD8+ and CD4+ T-cells in the tumors influences inhibitory IC, and is associated with cytokine-receptor signaling pathways across cancers." (PMID 39766097, 2024).
cancer (continued). "Heatmaps were used to illustrate the associations between CDKN3 expression and CD4 + T cells, cancer-associated fibroblasts, macrophages, and endothelial cells." (PMID 38720365, 2024). "Immune cell infiltration analysis presented that high LTF expression exhibited dysregulated immune infiltration (i.e., CD4 + T cells, neutrophils, macrophages, myeloid dendritic cells and cancer associated fibroblast)." (PMID 38763993, 2024). "RT53 and RT39 act as decoys that can prevent interaction between AAC11 and its binding partners and are known to elicit the cell death of cancer cells and of CD4+ T cells susceptible to HIV infection." (PMID 38543531, 2024). "IL-17 is a pro-inflammatory cytokine produced by CD4 + helper T cells and is strongly implicated in malignant tumor formation and metastasis." (PMID 38486102, 2024). "In CIC, TRLS was positively associated with cancer cell antigen release and negatively correlated with CD4 + T cell recruitment and cancer antigen presentation, consistent with the assessment of immune status and genomic alterations." (PMID 38519942, 2024). "The analysis revealed that AC-GV patients, despite having the poorest prognosis, exhibited the highest estimated enrichment score of TME cells, especially CD4+ T cells, M1 macrophages, activated dendritic cells, and cancer-associated fibroblasts (CAFs)." (PMID 39906742, 2024). "We developed Cox proportional hazard models with adjustment for known confounders of cancer risk and time-dependent cumulative and lagged exposures of CD4:CD8 ratio to account for time-evolving risk factors and avoid reverse causality." (PMID 38092042, 2024). "In the context of BRCA, elevated levels of FOXK2 correlate with increased numbers of cancer‐associated fibroblasts (CAFs) and heightened infiltration of CD4 + TH2 cells, thereby indicating a poorer prognosis." (PMID 39552461, 2024). "It was inversely linked to the relapse-free survival of B-cell-enriched cancer patients, while the converse was true for the cancer patients with low mutation burden, decreased B-cells, basophils and CD4+ T cells." (PMID 38241178, 2024). "Primary or secondary (i.e., acquired) resistance is a common occurrence in cancer patients and is often associated with high numbers of T regulatory (Treg) cells (CD4+CD25+FOXP3+)." (PMID 38318526, 2024). "It is usually a reactivation of latent infection and is associated with late-stage HIV among patients with CD4+ T-cell counts below 200 cells/μl although it has also been reported among patients on anti-cancer chemotherapy." (PMID 40190535, 2024). "Further analyses using the EPIC algorithm showed that infiltrations of B cells, cancer-associated fibroblasts (CAFs), CD4+ T cells,endothelial, macrophages, NK cells, and other cells were markedly different between GNAL-high and GNAL-low expression groups." (PMID 38686055, 2024). "Compared with the low group, the high FOXK2 expression group showed varying degrees of reduction in the infiltration of all immune cells except CD4 + Th2 cells and cancer associated fibroblasts (CAFs)." (PMID 39552461, 2024). "The most common factor identified as a risk for the occurrence of any cancer was advancing age reported by three studies, followed by low CD4 counts < 200 cell/μl documented by two studies." (PMID 38549952, 2024). "Recent analysis indicated that expression of cuproptosis-induced FDX1 negatively correlates with numbers of CD4 + T cells and cancer-associated fibroblasts (CAFs) infiltration." (PMID 39068453, 2024). "The CD8+PD-1+/CD4+PD-1+ index proposed in this previous study was based on the premise that high CD8+PD-1+ T cell levels are associated with good prognosis in cancer patients, whereas high CD4+PD-1+ T cell levels are associated with poor clinical outcomes." (PMID 38404585, 2024). "Pathogenic T-cell subsets, such as CD4 + T-cells, play pivotal roles in a variety of diseases, including cancers and autoimmune inflammatory conditions." (PMID 39574011, 2024).
cancer (continued). "Stronger correlations with the risk score were seen with Th2 CD4 + T cells, myeloid dendritic cells, macrophages M1, cancer-associated fibroblasts, and macrophages M2." (PMID 38735911, 2024). "This however results in an enigma: Y loss in CD4 + T lymphocytes is associated with increased risk of cancer, yet LOY occurs at relatively low levels in CD4 + T lymphocytes compared with other leukocytes." (PMID 38443832, 2024). "The findings indicated that M2 macrophage and memory CD4+ T cells were positively associated with the NETs‐related pattern among pan‐cancer, while Treg and memory B cells were inversely associated." (PMID 39730971, 2024). "It was associated with B cells in 15 types of cancer, with CD4+T cells in 9 types of cancer, with CD8+T cells in 16 types of cancer, with macrophages in 19 types of cancer, with neutrophils in 20 types of cancer, and with dendritic cells in 18 types of cancer." (PMID 38503865, 2024). "Our imaging approach will provide deeper insights into the underlying molecular mechanisms of CD4-directed cancer immunotherapies in preclinical mouse models and is applicable for clinical translation." (PMID 39239511, 2024). "Inhibitory CD4+ T cells have been linked with suboptimal immune responses against cancer and pathogen chronicity." (PMID 37440306, 2023). "Our study revealed that both ADIPOR1 and ADIPOR2 were positively associated with CD4+ T cell and negatively associated with NK cell in most cancers." (PMID 36896172, 2023). "Using the TIMER method, it was revealed that BUB1B is significantly associated with B cell, CD8+ T cell, CD4+ T cell, macrophage, neutrophil, and DC infiltration levels in different cancers." (PMID 37055476, 2023). "Patients with CD4 count <500 cells/mm3 and VL > 1000 copies/ml had a higher risk of acquiring OIs and malignancies." (PMID 37824698, 2023). "Our analyses revealed that endothelial cells, cancer-associated fibroblasts, monocytes, and the remaining CD4+ T cells were positively correlated with risk score." (PMID 37025405, 2023). "CD4+ T cell lymphopenia is also evident up to 10 years post-renal transplant, a long-term effect associated with accelerated renal allograft decline and a high risk of cancer development compared to non-CD4+ T cell lymphopenic patients." (PMID 36960048, 2023). "ACSL4 expression had a correlation with immune cells including CD4 + T cells, neutrophils, cancer associated fibroblasts (CAFs), macrophages and common lymphoid progenitors." (PMID 37193981, 2023). "Previous studies have demonstrated that in some cancer types, the infiltration of lymphocytes, especially CD4+ T cells and CD8+ T cells, was associated with the activation of immune responses and resulted in favorable prognosis." (PMID 37189627, 2023). "Immune correlation research revealed a significant relationship between the ZWINT gene and infiltrating immune cells, such as B cells, CD4+ T cells, cancer-associated fibroblasts, CD8+ T cells, macrophages, neutrophils, and NK cells." (PMID 37091844, 2023). "Given the pervasively positive correlation with risk scores across different cancer types, we elected to investigate the effect of the retinoic acid metabolism pathway on transition of CD4+ memory T cells." (PMID 38090588, 2023). "In EPIC algorithm, MTHFR is positively correlated with B-cells, cancer-associated fibroblasts (CAFs), CD4+T-cells, CD8+T-cells in almost tumors." (PMID 37354330, 2023). "This causes CD4+ T cells to be capable of recognizing cancer-associated antigens in a wider array than CD8+ T cells." (PMID 37508545, 2023). "The immune infiltration analysis revealed that EIF4A3 expression was negatively associated with CD8+ and CD4+ T cells and positively with myeloid-derived suppressor cells, macrophage M2, cancer-associated fibroblasts, and Treg cells." (PMID 37180585, 2023).
cancer (continued). "The high-risk score of the prognostic model was positively correlated with M2 macrophages, cancer-associated fibroblast, hematopoietic stem cell, and stromal score and negatively correlated with NK cell, cytotoxicity score, B cell, and T cell CD4+Th1." (PMID 37144238, 2023). "Specifically, NDC1 was significantly associated with T cells follicular helper in 11 cancer types, with Macrophages M1 in 16 cancer types and with T cells CD4 memory resting in 12 cancer types." (PMID 37733696, 2023). "The expansion of TAMs and MDSCs induces an iTME that promotes carcinogenesis, and low ratios of CD8+/CD4+ have been linked to poor prognosis in various human cancers including GC." (PMID 37572185, 2023). "We found high cytotoxic CD4+ T score is associated with a better overall survival in cancer patients (p = 0.0396)." (PMID 36869048, 2023). "Tregs represent an immunosuppressive subset of CD4+ T-cells that specifically counteract T-cells functions, thus contributing to the loss of cancer immunosurveillance." (PMID 36691794, 2023). "The TME surrounding SCC lesions is infiltrated with a high proportion of CD4+ T cells, which would be associated with spontaneous regression in other cancers such as primary melanoma and BCC." (PMID 37173918, 2023). "CD8+ T cells, CD4+ T cells, cancer-associated fibroblast, etc., were all strongly positively correlated with RBP1 in various tumors." (PMID 36970364, 2023). "It was worth noting that SPEN expression was negatively correlated with infiltration level of NKT and T-helper 1 (Th1) cells and positively correlated with CD4 + T cells, cancer-associated fibroblast (CAF) and regulatory T cells (Tregs) in many tumors." (PMID 37620924, 2023). "The presence of CXCL13-producing CD4+ T cells and the formation of TLSs were associated with improved survival in patients with several malignant tumors." (PMID 37762313, 2023). "The associations between the immune infiltration level of CD4+ cells and cancer-associated fibroblasts with GOLT1B expression were explored using TIMER2." (PMID 38130634, 2023). "Little experimental evidence was reported about ALDOA ‘s association with immunocytes in cancers, but its potential roles in B cells, CD4+ T cells, and Th cells were noticed by GSEA." (PMID 36494582, 2023). "Loss of iASPP in cancer cells, CD4+ T cells, or with germline deletion elicited strikingly elevated immune tolerance." (PMID 36746936, 2023). "Recently, mesothelial cells have been shown to form antigen-presenting cancer-associated fibroblasts (apCAFs), which in turn induce naive CD4+ T cells into regulatory T cells in pancreatic cancer." (PMID 37938580, 2023). "In cancer, MHCII-expressing cancer-associated fibroblasts can promote immunosuppression via activating CD4 T cells." (PMID 37371525, 2023). "Immune cells like natural killer cells, CD8+ T cells and type 1 helper CD4+ T (Th1) cells have strong anti‐cancer activity and are often linked to positive outcomes in human tumours." (PMID 38041544, 2023). "On the other hand, CD4+Treg cells subdue inflammation, promote tumorigenicity, and are associated with poor prognosis in cancer patients." (PMID 37568652, 2023). "In contrast to the cytotoxic CD8+ and the helper CD4+ T cells, Tregs are believed to play an undesired role to which cancer progression has been linked." (PMID 38044996, 2023). "Risk scores showed a significant positive association with most immune cells in the TME, such as M2 macrophages, cancer-associated fibroblasts, CD4+ T cells, and CD8+ T cells." (PMID 37445803, 2023). "Oppositely, FDX1 expression was negatively correlated with that of CD4+ T cells and cancer-associated fibroblasts (CAFs)." (PMID 36173462, 2023). "Nonetheless, in most cancers, including melanoma and head and neck, ovarian, cervical, and cholangiocarcinoma, a positive association was reported between high CD4+ TILs and OS and/or PFS." (PMID 36564565, 2023).